GPC3 (glypican 3)
Diseases named in the same sentence as GPC3 in open-access papers (continued):
Sharing a sentence is not in itself a finding about the gene and the disease.
tumor (continued). "The application of L3C7c‐Fc reversed the inhibition mediated by sPD‐L1, and the combination with the CAR NK 92 cell constructed with an affinity‐enhanced antibody targeting GPC3 achieved improved killing capacity toward HCC cells in the presence of sPD‐L1 or mPD‐L1 expressing tumor cells." (PMID 38045827, 2023). "H8B-BsAb, a novel tetravalent bispecific anti-GPC-3 antibody, showed significant anti-tumor effect in a xenograft mouse model of HCC, and may be a potential candidate for HCC therapy." (PMID 36773210, 2023). "In addition, higher GPC3 expression GC patients have higher TIDE (Tumour Immune Dysfunction and Exclusion) score, dysfunction and exclusion score." (PMID 37036308, 2023). "GPC3-CAR-T cells have been shown to effectively inhibit tumor growth in HCC xenograft models." (PMID 36307751, 2022). "The specific expression of GPC3 in tumor cells has received widespread attention." (PMID 35251989, 2022). "Indeed, GPC3 was reported to participate in tumor growth and promote epithelial-mesenchymal transition by impacting several signaling pathways, such as upregulation of the Wnt signaling, ERK pathway, YAP and hedgehog cascades." (PMID 35937502, 2022). "We evaluated GPC3 expression in human normal and tumor tissue specimens." (PMID 35507536, 2022). "Its positivity does not correlate with tumor size; in fact, even small tumors were GPC3 positive, making it a good early diagnostic marker for HCC." (PMID 36077433, 2022). "Similarly, frequent expression of GPC3 was found in tumours that were positive for EGFR (22.4%, 11 cases) and Ki67 (11.4%, 13 cases)." (PMID 36676710, 2022). "Moreover, administration of anti-GPC3 antibodies in a phase I clinical trial resulted in some tumor limiting capacity." (PMID 35454809, 2022). "In order to test whether the therapeutic benefit of the Ad-IL-12/GPC3 vaccine regimen in the tumor model depended on CD8+ T lymphocytes, we used anti-CD8 monoclonal antibodies (mAbs) to carry out a deletion test." (PMID 36139670, 2022). "From our data showing different TGI despite comparable GPC3 expression, we speculated that the presence of tumour-infiltrating immune cells at baseline may be critical to improve sensitivity of tumour to ERY974." (PMID 36071036, 2022). "Furthermore, a GPC3 vaccine has been found to infiltrate tumour tissue in paediatric tumours, and the antibody has been shown to stimulate solid tumour regression." (PMID 36676710, 2022). "In the Ad-IL-12/GPC3 group, the tumor inhibition rate was markedly increased, suggesting Ad-IL-12/GPC3 vaccine could suppress the tumor growth of the subcutaneous tumor models." (PMID 36139670, 2022). "To examine whether GPC3 expression is the sole biomarker for determining the efficacy of ERY974, we compared ERY974 efficacy between various tumour models with comparable GPC3 expression levels." (PMID 36071036, 2022). "The conventional LI-RADS categories for imaging-based classification of HCC were not sensitive to GPC3 expression in our study population, suggesting that tumor morphology and vascularity are not directly linked to GPC3 upregulation." (PMID 36518314, 2022). "Previous studies have revealed that GPC-3 is actively involved in regulating HCC tumor growth." (PMID 36091074, 2022). "Interestingly, the deletion of CD8+ T cells abolished tumor growth inhibition by Ad-IL-12/GPC3 treatment, suggesting that CD8+ T cell immune responses were required to eliminate the tumor." (PMID 36139670, 2022). "The anti-tumor effect of Ad-IL-12/GPC3 was evaluated in different tumor models." (PMID 36139670, 2022). "Similarly, researchers also developed logic-gated (log) GPC3-synNotch-inducible CD147 CAR to minimize any on-target/off-tumor toxicity." (PMID 36093115, 2022). "Despite the low expression of GPC3 in normal adult tissues, “on-target off-tumor” may lead to disastrous side effects." (PMID 35251989, 2022).
tumor (continued). "However, the immunogenicity of the GPC3 vaccine alone is weak, and it cannot effectively stimulate a strong anti-tumor immune response to treat HCC." (PMID 36139670, 2022). "Of all analyzed tumor markers, GPC3 showed the lowest expression in PHCs." (PMID 36077764, 2022). "GPC3 is known to be expressed in MCC but its association with tumor characteristics or prognosis has not been reported." (PMID 35937502, 2022). "Therefore, Ad-IL-12/GPC3 combined immunization significantly suppressed tumor development, reduced tumor weight, and improved the tumor inhibition rate of the immunized tumor model." (PMID 36139670, 2022). "As expected, GPC3 was remarkably down-regulated in LUAD tumor tissue and cells (A549 and H1975)." (PMID 35710585, 2022). "Thus, we constructed a bispecific CAR-T cell targeting the HCC tumor-specific antigen GPC3 and the inducible tumor-immunosuppressive antigen PD-L1." (PMID 35317524, 2022). "Moreover, GPC3 expression was mainly displayed in tumours that were positive for hormone and HER2 receptors." (PMID 36676710, 2022). "It is apparent that the GPC3-postivie HCC is softer (lower c-value) than the GPC3-negative tumor." (PMID 36518314, 2022). "Remarkably, IL-12 could be used as an adjuvant, significantly promoting the tumor antigen-specific immune responses to GPC3." (PMID 36139670, 2022). "In addition, the humanized form of the antibody was able to induce ADCC and complement-dependent cytotoxicity (CDC) in GPC3-expressing tumor cells." (PMID 36077433, 2022). "Notably, the lysis rate of double-positive tumor cells showed that the cytotoxic activity of CoG133-CAR T cells was significantly enhanced compared with that of GPC3-CAR T cells and CD133-CAR T cells." (PMID 35879685, 2022). "Similarly, we observed that the cells in cluster 16 and 30 were all derived from non-tumor liver and highly expressed in GPC3 and CD24; thus, they were annotated as hepatocytes." (PMID 36605219, 2022). "In addition, GPC3-CAR-T cells can infiltrate mouse tumor tissue and persist as effector memory T cells." (PMID 36291802, 2022). "Therefore, we predicted that multifunctional CD8+ T lymphocytes are necessary for the anti-tumor effect induced by Ad-IL-12/GPC3 vaccine." (PMID 36139670, 2022). "H&E and GPC3 histology show more a robust cancer phenotype in PDX tumor models." (PMID 34497364, 2021). "Although the TJ12P2 peptide could greatly accumulate in GPC-3 positive tumor tissues, there was still some moderate diffusion of residue probes in the abdominal cavity which might be considered as background signals." (PMID 34150644, 2021). "However, GPC3 is upregulated in a variety of tumor entities including HCC, and its expression is reportedly associated with poor prognosis." (PMID 34359547, 2021). "Development of GPC-3/EGFR, GPC-3/ASGR1, and αFP /MHC complex CAR-T cells has been associated with improved activation, expansion, and persistence of the T cells, as well as stronger cytotoxicity in double-positive tumor cell groups." (PMID 34696292, 2021). "In vivo studies showed that CCL19 overexpression within the tumor could effectively recruit CAR-T cells targeting GPC3, an HCC-specific antigen, to infiltrate tumor tissue and better inhibit tumor tissue growth." (PMID 34527749, 2021). "Since GPC3 is more frequently observed in moderately and poorly differentiated HCC tumor cells, which are more prone for extrahepatic spreading, the presence of GPC3+ CTCs may inform about a de-differentiated metastatic HCC." (PMID 34884878, 2021). "However, evidence has shown that GPC3 is overexpressed in 14% of gastrointestinal tract and pancreatic carcinomas/neoplasms." (PMID 34822533, 2021). "However, mutations or loss of expression have been reported in Simpson-Golabi-Behmel syndrome, ovarian carcinoma, breast cancer, and mesothelioma, suggesting that GPC3 functions as a tumour-suppressor gene." (PMID 34112123, 2021).
tumor (continued). "GPC3 is a membrane protein located on the surface of tumor cells." (PMID 34513678, 2021). "Although shown to be generally widely expressed on HCC, the extent of GPC3 expression varies and may limit the sensitivity of the tumor volume quantification and efficacy of RIT for all HCCs observed in clinical practice." (PMID 33580090, 2021). "Interestingly, the GPC3 gene regulates cell proliferation as a tumor suppressor gene in LUAD but shows the opposite effect in LUSC." (PMID 35069695, 2021). "However, in tissues that only express GPC3 in the embryonic stage, it tends to reappear when there is a malignant transformation into a tumor whereas GPC3-heavy tissues in adults show reduced levels of GPC3 in a malignant situation." (PMID 33742285, 2021). "Moreover, a phase I clinical trial that combines anti-GPC3 antibody with immune checkpoint inhibitors (anti-PD-L1 antibodies) has shown well-tolerated immune response and potential anti-tumor activity in GPC3-overexpressing HCC." (PMID 33878524, 2021). "Moreover, GPC3 differs from other tumor markers by a significantly higher PLR index, which makes it promising for combined use." (PMID 34513063, 2021). "Indeed, GPC-3 binding to growth factors such as IGF-2 in different tumor cell types affects these cells’ survival, as GPC3 can induce apoptosis or inhibit proliferation in a cell line-specific manner, and these cells can be rescued by IGF-2 signaling." (PMID 34069554, 2021). "Additionally, GPC3, one of the tumor-associated antigens, elevated F4/80 + CD86+ macrophage (M1) percentage within tumor, in the meantime of inducing CD8+ T cell immune response specific to GPC3." (PMID 34112138, 2021). "AFP and GPC3, which are known tumor markers for HCC, were classified as A genes." (PMID 33539378, 2021). "Meanwhile, MXR7 (GPC3) cDNA has a high positive rate in tumor tissues of patients with HCC." (PMID 33726759, 2021). "This study verified the cytotoxicity of GPC3 CAR-T cells against three HCC tumor cells in vitro." (PMID 34527749, 2021). "GPC3 upregulation was also seen at the protein level by western blot with some variation in protein expression and presence of heparin sulfate (HS) side chain or 40-kDa cleavage product for some HB tumor and PDX samples." (PMID 34497364, 2021). "One clinical research of glypican-3 (GPC3) peptide vaccine in the treatment of HCC patients revealed that GPC3 peptide vaccine had good tolerance and anti-tumor effect, as well as could prolong the overall survival time of patients." (PMID 34513678, 2021). "Thus, its excellent tumor specificity and cell-membrane localization make GPC-3 a promising biomarker for precise diagnosis and targeting therapy of HCC." (PMID 34150644, 2021). "A study in 2020 indicated that ERY974 was effective in suppressing GPC3-expressing tumor growth." (PMID 34922633, 2021). "Therefore, the authors sought to direct the ADCP-enhancing activity of targeting CD47 to GPC3+ tumor cells using a bispecific approach." (PMID 34069573, 2021). "However, studies found that the relationship between GPC3 and Wnt/β-catenin in malignant tumors varies according to tumor types." (PMID 34458143, 2021). "Co-culture of GPC3+ tumor cells, MSCsGPC3-CD3 and T lymphocytes led to the increased production of IFN-γ in GPC3-specific CD4+T cells and the enhanced activation and expansion of GPC3-specific CTLs, which resulted in the efficient CTL-dependent killing of GPC3-expressing malignant cells." (PMID 34830312, 2021). "However, the LIHC network does contain a module with 114 genes (MCODE score 94.3), 33 of which are in the GPC3-containing cluster identified from the non-tumor network (17 of these genes are directly connected with GPC3 in the non-tumor network)." (PMID 31956905, 2020). "Furthermore, the results of in vitro and in HCC tumor bearing mouse models confirmed that CIMs inherited the excellent tumor targeting ability from GPC3 specific CAR-T cells and possessed significant photothermal antitumor abilities." (PMID 31938065, 2020).
tumor (continued). "Patients with cancers positive for both antigen proteins, i.e., HSP70 and GPC3, tended to present a better overall survival (P = 0.08), and tumor markers were reduced more often in patients with peptide-specific CTL induction for at least one of the two peptides (P = 0.031)." (PMID 32219501, 2020). "In certain cases, HSP70 and GPC3 expression levels were complementary within the same tumor." (PMID 32219501, 2020). "In the current study, the expression of GPC3 was correlated only with tumor size." (PMID 32582830, 2020). "We explored expression patterns of GPC3 with regards to the 14 tumor types." (PMID 31956905, 2020). "Even if targeting GPC3 strategy could eliminate all GPC3-positive cells, GPC3-negative tumor may grow under such treatment pressure and become resistant." (PMID 32127929, 2020). "By contrast, glypican-3 (GPC3) has been reported to act as a tumor suppressor." (PMID 33330449, 2020). "GPC3 was currently evaluated as a potential target for tumor specific therapy and immunotherapy." (PMID 32582830, 2020). "GPC3 also plays an important regulatory role in tumor metastasis." (PMID 32127929, 2020). "GPC3 is involved in the reprogramming of tumor cell metabolism by acting on the glucose pathway." (PMID 32585931, 2020). "In all cases, tumor cells expressed either HSP70 or GPC3 in both primary and metastatic lesions." (PMID 32219501, 2020). "Glypican-3 is a unique protein specifically expressed in HCC cells and the high level of glypican-3 expression may indicate tumor malignancy and predict the patient's prognosis." (PMID 32294701, 2020). "Furthermore, GPC3-derived epitope peptide conjugated to liposomes seemed to be able to induce CTLs to inhibit the growth of GPC3-expressing tumor." (PMID 31888198, 2019). "Nevertheless, we were able to glean useful data from this trial: in one case the HCC tissue became inflamed and then necrotic after two injections of the vaccine, despite ongoing liver dysfunction; and we established GPC3 peptide-specific CTL clones from a tumor biopsy specimen." (PMID 31024850, 2019). "Recent breakthroughs including the structural modeling of GPC3 and GPC3–Wnt complexes represent important steps toward deciphering the molecular mechanism of action for GPC3 and how it may regulate cancer signaling and tumor growth." (PMID 31428581, 2019). "An alternative theory might be that the significant inverse correlation of tGPC3 and eGPC3 in patients with GEA is based on the active suppression of the presence of GPC3 in the systemic circulation by tumor cells." (PMID 31100935, 2019). "GPC3 would be a promising tumor marker for diagnosing N-HCC." (PMID 31635078, 2019). "Hence, the mechanism of influence of CK19/GPC3 sub-typing towards the aggressive biological behavior of tumor cells should be focused." (PMID 31676847, 2019). "These GPC3-specific imaging methods could provide an accurate assessment of tumor responses to GPC3-targeted therapy and, more importantly, allow the early detection of GPC3-expressing HCC suitable for the GPC3-targeted therapy in the future." (PMID 31510063, 2019). "In addition to serum levels of GPC3, we also examined the expression profiles of GPC3 and other promising prognostic indicators in tumor samples of N-HCC." (PMID 31635078, 2019). "Moreover, miR-4510 functions as a tumor suppressor since it directly targets the glypican-3 (GPC3) oncogene and impairs the Wnt/β-catenin pathway." (PMID 30909459, 2019). "GPC3 functions entirely differently in various types of tumours." (PMID 31160489, 2019). "In other words, GPC3 may be a promising serum tumor marker for early detection and diagnosis of N-HCC." (PMID 31635078, 2019). "Considering the critical role of reprogrammed glucose metabolism in tumor progression, we hypothesized that GPC3-regulated glucose metabolism could be involved in the promotion of growth and metastasis in LC cells." (PMID 31781603, 2019).
tumor (continued). "Overexpression of GPC3 in serum or tumor tissue predicts poor prognosis in patients with LC." (PMID 31781603, 2019). "There are also several studies determining the role of GPC-3 on tumor growth." (PMID 31391540, 2019). "This and other evidence suggested that GPC3 could be a potentially promising tumor marker for the diagnosis of HCC." (PMID 31635078, 2019). "In addition, correlation analyses showed that the density of GPC3-CAR T cells in mouse peripheral blood significantly (P < 0.05) negatively correlated with the tumor burdens in both treatment groups of wild-type and PD-1-deficient GPC3-CAR T cells." (PMID 30327605, 2018). "Downregulation of GPC3 has already been detected in ovarian carcinoma, breast cancer, and mesothelioma, suggesting that it may act as a tumor suppressor gene in these tissues." (PMID 30027065, 2018). "In this study, we reported that, given adequate exposure of codrituzumab, the combination of high GPC3 expression in tumor cells and high CD16 expression on NK cells from peripheral blood at baseline was associated with codrituzumab clinical efficacy in terms of overall survival." (PMID 29535817, 2018). "In addition, preliminary evidence for potential anti-tumor activity was observed in patients with high expression of GPC3." (PMID 29508107, 2018). "The decrease in tumor uptake after peak localization at 24 to 48 h appears to be unusual, although seen in pre-clinical imaging with a Zr-89-labeled antibody targeting the same GPC3 in primary HCC orthotopic xenografts." (PMID 29508107, 2018). "Interestingly, GPC3 immunohistochemistry analysis demonstrated a strong staining in normal mucosa and a cytoplasmic staining in tumor cells." (PMID 30027065, 2018). "The Immunohistochemical staining with an antibody that recognises the early diagnostic tumour marker GPC3 showed that liver tissues from non-transplanted rats and rats transplanted with HepG2 –UC-MSCs sheets had no staining." (PMID 28850615, 2017). "The remaining tumor islets expressed GPC3 at similar levels as the untreated group." (PMID 27419635, 2017). "In a phase 1 study published in 2012, two glypican-3 (GPC3) derived peptides restricted for HLA-A phenotypes induced specific CD8+ cells tumour infiltration; a peptide-specific cytotoxic T response was associated with longer OS, but only one out of 33 treated patients reached an objective response." (PMID 28758114, 2017). "Additionally, the incidence of Klrk1+/+mice developing tumours with the highest IHC score (score 3) was mildly increased compared with Klrk1−/−mice (19% versus 11.1% for GS; 9.6% versus 3.7% for Glypican-3 and 19% versus 11.1% for HSP70 respectively)." (PMID 28128200, 2017). "Collectively, these findings suggest that this anti-GPC3 BiTE might be a promising anti-tumor reagent for patients with GPC3-positive HCC." (PMID 28881778, 2017). "Finally, the tumor suppressive effect of the most promising GPC3-regulating miRNA was further investigated using molecular and functional tools, as well as the chick chorioallantoic membrane model." (PMID 28476031, 2017). "However, fibrous stroma among the tumor nests was very rich compared to that in CK19−/GPC3+ and CK19−/GPC3− groups." (PMID 26977595, 2016). "On the other hand, GPC3 overexpression significantly decreased MDA-MB231 tumor incidence." (PMID 27507057, 2016). "However, histopathology revealed that GPC3 overexpressing tumors had a large necrotic core, inducing an overestimation of the final tumor volume (inset)." (PMID 27507057, 2016). "Additionally, the cytotoxic effect of CARgpc3 T cells on GPC3-positive tumor cells is positively correlated with the effector: target ratios." (PMID 26684028, 2016). "Therefore, in this study, we explored the antitumor potential of third-generation glypican 3 (GPC3)-redirected chimeric antigen receptor (CAR)-engineered T lymphocytes (CARgpc3 T cells) in tumor models of LSCC." (PMID 26684028, 2016).